CDYL (chromodomain Y like)
Description:
[Isoform 2]: Chromatin reader protein that recognizes and binds histone H3 trimethylated at 'Lys-9', dimethylated at 'Lys-27' and trimethylated at 'Lys-27' (H3K9me3, H3K27me2 and H3K27me3, respectively). Part of multimeric repressive chromatin complexes, where it is required for transmission and restoration of repressive histone marks, thereby preserving the epigenetic landscape. Required for chromatin targeting and maximal enzymatic activity of Polycomb repressive complex 2 (PRC2); acts as a positive regulator of PRC2 activity by bridging the pre-existing histone H3K27me3 and newly recruited PRC2 on neighboring nucleosomes. Acts as a corepressor for REST by facilitating histone-lysine N-methyltransferase EHMT2 recruitment and H3K9 dimethylation at REST target genes for repression. Involved in X chromosome inactivation in females: recruited to Xist RNA-coated X chromosome and facilitates propagation of H3K9me2 by anchoring EHMT2 (By similarity). Promotes EZH2 accumulation and H3K27me3 methylation at DNA double strand breaks (DSBs), thereby facilitating transcriptional repression at sites of DNA damage and homology-directed repair of DSBs. Required for neuronal migration during brain development by repressing expression of RHOA (By similarity). By repressing the expression of SCN8A, contributes to the inhibition of intrinsic neuronal excitability and epileptogenesis (By similarity). In addition to acting as a chromatin reader, acts as a hydro-lyase. Shows crotonyl-coA hydratase activity by mediating the conversion of crotonyl-CoA ((2E)-butenoyl-CoA) to beta-hydroxybutyryl-CoA (3-hydroxybutanoyl-CoA), thereby acting as a negative regulator of histone crotonylation. Histone crotonylation is required during spermatogenesis; down-regulation of histone crotonylation by CDYL regulates the reactivation of sex chromosome-linked genes in round spermatids and histone replacement in elongating spermatids (By similarity). By regulating histone crotonylation and trimethylation of H3K27, may be involved in stress-induced depression-like behaviors, possibly by regulating VGF expression (By similarity). [Isoform 1]: Not able to recognize and bind histone H3K9me3, histone H3K27me2 and histone H3K27me3, due to the presence of a N-terminal extension that inactivates the chromo domain. [Isoform 3]: Not able to recognize and bind histone H3K9me3, histone H3K27me2 and histone H3K27me3, due to the absence of the chromo domain. Acts as a negative regulator of isoform 2 by displacing isoform 2 from chromatin.
Synonyms: CDYL1; DKFZP586C1622
Tractability: Small molecule: a high-quality ligand is known; it has a binding pocket of medium quality. PROTAC: ubiquitination databases record sites on it; its protein half-life has been measured; a small molecule that binds it is known.
Target class: Epigenetic regulator; Reader; Methyl-lysine/arginine binding protein; Chromodomain
Gene: Protein-coding gene on chromosome 6 (4,706,159 to 4,955,551, forward strand). Ensembl gene ENSG00000153046.
Subcellular location: Nucleus (Isoform 2); Chromosome
Subcellular location (Human Protein Atlas): Nuclear speckles
Gene Ontology:
Molecular function: (2E)-butenoyl-CoA hydratase activity; protein binding; protein-macromolecule adaptor activity; transcription corepressor activity; chromatin binding; histone H3K27me3 reader activity; histone H3K9me2/3 reader activity
Biological process: negative regulation of peptidyl-lysine crotonylation; random inactivation of X chromosome; spermatid development; spermatogenesis; negative regulation of DNA-templated transcription
Cellular component: chromosome; nuclear speck; nucleus; cytoplasm
Genetic constraint (gnomAD): Loss-of-function variants: 7 observed, 44.95 expected, observed/expected ratio (o/e) 0.16, 90% interval 0.088 to 0.29. The upper end of that interval is the gene's LOEUF score, 0.29, which puts it in group 1 of 6, group 1 being the genes least tolerant of losing a copy. Missense variants: 458 observed, 721.45 expected, observed/expected ratio (o/e) 0.63, 90% interval 0.59 to 0.69. Synonymous variants: 262 observed, 273.65 expected, observed/expected ratio (o/e) 0.96, 90% interval 0.87 to 1.06.
Homologues: Orthologues: macaque CDYL (99% identical), chimpanzee CDYL (98% identical), zebrafish cdyl (67% identical), Drosophila melanogaster Dci (13% identical), Caenorhabditis elegans B0272.4 (12% identical), Drosophila melanogaster CG8778 (12% identical), Caenorhabditis elegans ech-5 (11% identical), Drosophila melanogaster HIPP1 (10% identical), Drosophila melanogaster CG14787 (10% identical), Drosophila melanogaster Srlp (10% identical), Caenorhabditis elegans ech-3 (9% identical), Drosophila melanogaster CG5611 (9% identical). Paralogues in human: CDY1B (62% identical), CDY2A (62% identical), CDY2B (62% identical), CDY1 (62% identical), CDYL2 (49% identical), ECHS1 (15% identical), ECHDC3 (14% identical), ECHDC2 (14% identical), AUH (13% identical), ECH1 (12% identical), ECHDC1 (12% identical), HIBCH (12% identical), and 1 more.
Diseases named in the same sentence as CDYL in open-access papers:
CDYL is named in the same sentence as 27 diseases in open-access papers, as found by Europe PMC text mining. Sharing a sentence is not in itself a finding about the gene and the disease. The quoted sentences say what the papers report.
depression (5 papers, 2021 to 2025). "Overexpression of CDYL in PL can increase the susceptibility of mice to depression, while knockdown of CDYL can reduce the susceptibility of mice to depression." (PMID 39606030, 2024). "Conversely, when CDYL is knocked down, the susceptibility of mice to depression is reduced." (PMID 38331935, 2024). "When overexpresses CDYL in PL, it can increase the susceptibility of mice to depression." (PMID 38331935, 2024). "It has been found that the expression levels of histone crotonylation hydrolase and transcription inhibitor, CDYL, are significantly increased in the prelimbic cortex (PL) in a mouse model of stress-induced depression." (PMID 39606030, 2024). "CDYL mediates histone crotonylation, which regulates gene transcription and promotes the development of stress‐induced depression in rodents, providing a potential therapeutic target for major depression." (PMID 37143582, 2023). "Thus, CDYL-mediated reduction of histone Kcr played a critical role in regulating stress-induced depression." (PMID 34262024, 2021). "In conclusion, the CDYL-VGF axis disrupts the structural synaptic plasticity in the mPFC, leading to behavioral depression." (PMID 38331935, 2024). "High-throughput sequencing of RNA transcriptome showed that CDYL can affect synaptic plasticity by transcriptionally inhibiting the expression of neuropeptide VGF, thereby regulating the occurrence and development of stress-mediated depression." (PMID 38331935, 2024).
small cell lung carcinoma (4 papers, 2019 to 2022). Small cell lung cancer (SCLC) is a highly aggressive malignant neoplasm, accounting for 10-15% of lung cancer cases, characterized byrapid growth, and early metastasis. "The verification results of quantitative PCR, and immunohistochemistry showed that we successfully constructed the small cell lung cancer cell model with an up-regulated expression of CDYL (H69AR-MMP9, H446DDP-MMP9)." (PMID 35431936, 2022).
epilepsy (2 papers, 2017 to 2018). A brain disorder characterized by episodes of abnormally increased neuronal discharge resulting in transient episodes of sensory or motor neurological dysfunction, or psychic dysfunction. "CDYL deficiency has been shown to disrupt neuronal migration and to influence susceptibility to epilepsy in mice." (PMID 30009487, 2018). "While SCN8A null heterozygotes exhibited less seizure susceptibility when compared to wild-type littermates, injecting lentiviruses carrying CDYL-shRNA to SCN8A null heterozygotes abolished the changes of epilepsy susceptibility in these mice." (PMID 28842554, 2017). "Co-injecting lentiviruses carrying CDYL-shRNA-GFP and SCN8A-shRNA-mCherry reversed the behavioral alteration in seizure susceptibility induced by knock-down of CDYL, suggesting that CDYL regulates epilepsy susceptibility mainly through Nav1.6 sodium channels." (PMID 28842554, 2017). "Here the authors show that the epigenetic factor CDYL regulates the gene expression of the voltage gated sodium channel, Nav1.6, which contributes to seizures in a rat model of epilepsy." (PMID 28842554, 2017).
hepatocellular carcinoma (2 papers, 2021 to 2022). A malignant tumor that arises from hepatocytes. "The interaction between G9a and CDYL is crucial in driving hepatocellular carcinoma (HCC) tumor progression." (PMID 35740522, 2022).
infertile (2 papers, 2020 to 2021). "Consequently, knockout of CDYL results in a severe progressive infertility in male mice due to the deficiency in spermatogonia maintenance." (PMID 32373210, 2020). "The relative abundance in transcripts of few TH2B associated genes- CREM, CDYL, PRKAG2, CATSPERB, TSGA10 and TSSK1B was studied in sperm of fertile and infertile men with asthenozoospermia-, oligozoospermia- or oligoasthenozoospermia." (PMID 33933143, 2021). "In light of this information, increased expression of CDYL observed in all the subgroups of infertile men with significantly increased expression in men with oligoasthenozoospermia group where both motility and sperm numbers are affected, is noteworthy." (PMID 33933143, 2021). "CDYL expression was found to be significantly higher in men with oligoasthenozoospemia (p = 0.009), while it was not altered in the other two subgroups of infertile men." (PMID 33933143, 2021).
metastatic disease (2 papers, 2019 to 2020). "Recently, a gene expression profiling study identified CDYL as one of the fourteen differentially expressed genes between breast tumors with and without visceral metastatic disease." (PMID 32373210, 2020).
Azoospermia (1 paper, 2024). Absence of any measurable level of sperm,whereby spermatozoa cannot be observed even after centrifugation of the semen pellet. "CDYL acts as a co-regulator of AR transactivation, and its expression is decreased in the Sertoli cells of human testes from patients with azoospermia." (PMID 38786072, 2024).
breast carcinoma (1 paper, 2025). "CircCDYL, a circRNA derived from the back‐splicing of CDYL exon 4, has an emerging role in breast cancer (BC) biology." (PMID 40702809, 2025). "CircCDYL, a circRNA derived from the back‐splicing (BS) of CDYL exon 4, has emerged as a circRNA significantly involved in breast cancer (BC) biology and is one of the most abundant circRNAs in luminal BC." (PMID 40702809, 2025). "We investigated the synergic role of the circRNA circCDYL and the splicing factor hnRNPL in modulating alternative splicing and isoform switch in breast cancer cells, with a focus on circCDYL and hnRNPL‐mediated isoform switch events involving the CDYL gene." (PMID 40702809, 2025).
glioma (1 paper, 2024). A benign or malignant brain and spinal cord tumor that arises from glial cells (astrocytes, oligodendrocytes, ependymal cells). "However, in a study by Kong and colleagues, CDYL revealed an association with immunosuppression within glioma cells." (PMID 39519018, 2024). "CDYL expression was shown to be elevated in glioma and in chemoresistant small-cell lung carcinoma, where its overexpression was associated with an advanced clinical stage and poor prognosis." (PMID 39519018, 2024). "The data indicated that CDYL depletion decreased glioma development and promoted immune pathways and expression of chemokine ligands (e.g., chemokine [C-C motif] ligand 2 [CCL2])." (PMID 39519018, 2024). "The authors proposed that CDYL may serve as a potential candidate therapeutic target in glioma." (PMID 39519018, 2024).
Macrocephaly (1 paper, 2023). Occipitofrontal (head) circumference greater than 97th centile compared to appropriate, age matched, sex-matched normal standards. "Studies on the effects of PRC2 dysregulation and its interaction with CDYL provide support to the idea of increased neuronal arborization as a mechanism underlying PRC2-associated macrocephaly." (PMID 36845425, 2023).
mantle cell lymphoma (1 paper, 2020). Mantle cell lymphoma is a rare form of malignant non-Hodgkin lymphoma affecting B lymphocytes in the lymph nodes in a region called the ``mantle zone''. "Remarkable overexpression of circ-CDYL was detected in the plasma of mantle cell lymphoma (MCL) and multiple myeloma (MM) patients." (PMID 33069241, 2020).
medulloblastoma (1 paper, 2021). A malignant, invasive embryonal neoplasm arising from the cerebellum. "The seven circRNAs, FKBP8, SMARCA5, GLIS1, BACH1, ZKSCAN1, CDYL, and OGDH, with a reduced expression in medulloblastoma versus cerebellum, while their corresponding linear mRNAs do not follow this change of expression pattern, were selected for further analysis." (PMID 34680287, 2021).
melanoma (1 paper, 2021). A malignant, usually aggressive tumor composed of atypical, neoplastic melanocytes. "On the other hand CYT-low metastatic melanomas had recurrent amplifications in loci 5p15.33 (TERT), 6p25.1 (CDYL), 7p22.2 (RAC1), 12q15 (MDM1) and recurrent deletions in 5q31.2 (CTNNA1, FGF1), 11q22.3 (FDX1, RDX, ZC3H12C), and 15q14 (RASGRP1, CSNK1A1P1, SPRED1)." (PMID 33779796, 2021).
neuropathic pain (1 paper, 2022). Chronic pain caused by damage to nerve fibers. "In addition, a novel CDYL antagonist UNC6261 can produce analgesic effect in neuropathic pain model." (PMID 35119221, 2022).
Sepsis (1 paper, 2024). Sepsis is defined as life-threatening organ dysfunction caused by a dysregulated host response to infection. "Circ-0008285 (located in exons of CDYL), showed significant upregulation in severe sepsis with an FC of 13.7, and Bonferroni-corrected P < 0.05/5." (PMID 39071490, 2024). "According to the qPCR results, we validated circRNAs such as hsa-circ-0008285 (exons of CDYL) and hsa-circ-0001811 (exons of STAU2) as potential biomarkers for severe sepsis." (PMID 39071490, 2024).
Sertoli Cell-Only Syndrome (1 paper, 2024). A type of male infertility in which no germ cells are visible in any of the biopsied SEMINIFEROUS TUBULES (type I) or in which germ cells are present in a minority of tubules (type II). "In this study, we observed low expression of CDYL in human Sertoli cells, early-stage spermatogonia, and spermatocytes with deficient spermatogenesis in the testes of patients with Sertoli cell-only syndrome and maturation arrest, similar to its expression in ARKO mouse testes." (PMID 38786072, 2024). "We examined the expression of AR and CDYL in normal and pathological human testes (Sertoli cell-only syndrome and maturation arrest) by immunochemistry." (PMID 38786072, 2024). "While the AR protein was expressed, the CDYL protein expression was negligible in the testes of patients with Sertoli cell-only syndrome." (PMID 38786072, 2024).
temporal lobe epilepsy (1 paper, 2017). A localization-related (focal) form of epilepsy characterized by recurrent seizures that arise from foci within the temporal lobe, most commonly from its mesial aspect. "Finally, examination of human temporal lobe epilepsy (TLE) brain tissues reveals decreased expression of CDYL and increased expression of SCN8A, supporting the important role of CDYL in suppressing epileptogenesis." (PMID 28842554, 2017). "Finally, examination of human brain tissues reveals decreased CDYL and increased SCN8A in the temporal lobe epilepsy group." (PMID 28842554, 2017).
tumor (16 papers, 2018 to 2025). "More specifically, CDYL knockdown evoked the influx of CCL2-recruited monocytes/macrophages and M1-like TAMs (tumor-associated macrophages/microglia) with antitumor activities." (PMID 39519018, 2024). "The expression of circ-CDYL is significantly downregulated in WT tissues compared to adjacent non-tumor tissues and upregulation of circ-CDYL inhibited cell proliferation, migration, and invasion." (PMID 35116058, 2021). "CDYL has been proved participating in several physiological activities, including neuronal migration, neural development, transformation of tumor cells, even the X chromosome inactivation." (PMID 32158757, 2020). "Significantly larger tumour volumes and significantly higher growth rates were observed in the CDYL overexpression group than in the corresponding control group after chemotherapy treatment." (PMID 31367252, 2019). "Collectively, high CDYL levels correlate with a worse response to chemotherapy, poor survival, and more advanced tumour stages in patients with SCLC." (PMID 31367252, 2019). "Simultaneously, CDYL knockdown restricted the presence of tumor-promoting M2-like TAMs." (PMID 39519018, 2024). "Similarly, xenograft experiments also showed that the increased xenograft growth and tumour volumes observed after CDYL overexpression in H69 cells were significantly inhibited by the combination of GSK126 and chemotherapy." (PMID 31367252, 2019). "In contrast, CDYL knockdown significantly reduced the tumour volumes and growth rates." (PMID 31367252, 2019). "Finally, cluster 4 is distinguished by a low point mutation burden (~80 coding mutations per tumor), as well as high expression of three genes (BTBD9, CDYL, TFAP2A) and high methylation at 100 promoters." (PMID 30367051, 2018). "The identified gene expression signature included 14 genes, five (CDYL, ATP6V0A4, PREP, RTN41P1, BEND3 and Kif18A) of which were up-regulated in the group of primary tumours of the patients with visceral organ metastasis." (PMID 30961553, 2019). "In addition, the activation of the HDGF-PI3K-AKT-mTOR axis could also be inhibited after decreasing m6A through the disrupted Circ-CDYL biogenesis mediated by m6A/YTHDC1 and the m6A/hnRNPA2/B1-mediated active sorting of Circ-CDYL into exosomes, ultimately attenuating tumor malignancy." (PMID 40136363, 2025). "We also performed Western blot analyses to detect the levels of CDYL, EZH2, and CDKN1C in xenograft tumours, and GSK126 significantly increased CDKN1C levels in CDYL-overexpressing H69 cells, but did not significantly change CDYL levels." (PMID 31367252, 2019).
cancer (5 papers, 2014 to 2024). A tumor composed of atypical neoplastic, often pleomorphic cells that invade other tissues. "In a hypoxic microenvironment, HIF1⍺ induced the transcription of circ-CDYL, thereby promoting the lung metastasis of circulating cancer stem cells." (PMID 39030638, 2024). "While the role of CDYL2 in malignant tumors is scarcely documented, CDYL (chromodomain Y like), a member of the CDYL family, has been reported to govern the post-translational modification of RPA1, thereby influencing HR repair." (PMID 38654320, 2024).
infection (1 paper, 2017). The state of being infected such as from the introduction of a foreign agent such as serum, vaccine, antigenic substance or organism. "The results showed that infection of CDYL-shRNA lentiviruses significantly lowered the AP threshold, whereas other intrinsic membrane properties of neurons were not affected." (PMID 28842554, 2017). "Consistent with the function of CDYL as a transcriptional corepressor, infection of lentiviruses carrying CDYL-shRNA resulted in increased expression of the majority of CDYL target genes in mouse hippocampus." (PMID 28842554, 2017). "Neither the morphology nor resting membrane potentials (RMPs) of neurons were changed with CDYL-shRNA infection (CDYL-shRNA infected neurons RMP, −77.91 ± 0.58, n = 34; nonsilencing-shRNA infected neurons RMP, −77.23 ± 0.89, n = 20; non-infected neurons RMP, −78.08 ± 0.48, n = 33)." (PMID 28842554, 2017).
CDYL also shares sentences with these, for which no sentence is quoted: acute myocardial infarction (2 papers); asthenozoospermia (1); breast tumors (1); heart failure (1); liver fibrosis (1); male infertility (1); teratozoospermia (1).